RNU7-66P (RNA, U7 small nuclear 66 pseudogene)
Synonyms: U7.66
Gene: Small nuclear RNA gene on chromosome 6 (66,728,843 to 66,728,904, reverse strand). Ensembl gene ENSG00000238949.
Homologues: Orthologues: chimpanzee U7 (100% identical), macaque U7 (97% identical). Paralogues in human: RNU7-19P (87% identical), RNU7-125P (85% identical), RNU7-73P (85% identical), RNU7-1 (82% identical), RNU7-14P (82% identical), RNU7-30P (82% identical), RNU7-35P (82% identical), RNU7-37P (82% identical), RNU7-70P (82% identical), RNU7-143P (81% identical), RNU7-20P (81% identical), RNU7-25P (81% identical), and 142 more.